LEP (leptin)
Diseases named in the same sentence as LEP in open-access papers (continued):
Sharing a sentence is not in itself a finding about the gene and the disease.
lung cancer (continued). "In vitro studies showed that leptin enhanced production of soluble intercellular adhesion molecule-1 (ICAM-1) in lung cancer cells through triggering a signaling cascade involving JAK1/2, STAT3, FAK, ERK, and GSK3αβ." (PMID 38571500, 2024). "Leptin indirectly regulates immune function in the lung cancer bone metastasis microenvironment by affecting the function of other cells." (PMID 38571500, 2024). "The following sections will discuss the mechanisms of action of leptin, adiponectin, Nesfatin-1, Resistin, chemerin, and visfatin in lung cancer bone metastasis." (PMID 38571500, 2024). "Leptin can inhibit the activity of macrophages and natural killer cells, reducing their ability to kill lung cancer cells." (PMID 38571500, 2024). "Conversely, other studies reported reduced serum leptin levels in lung cancer patients compared to the control group." (PMID 38534454, 2024). "Ultimately, lung cancer cells can escape immune surveillance by regulating the leptin signaling pathway, thereby promoting the occurrence and development of lung cancer bone metastases." (PMID 38571500, 2024). "Beyond its effects on T cells, leptin maintains the homeostasis of murine B cells by inducing Bcl-2 and cyclin D1, promoting cell cycle entry and preventing apoptosis, thereby promoting lung cancer cell proliferation." (PMID 38571500, 2024). "A study on A549 human lung cancer cell lines shows that leptin can significantly enhance the expression of transforming growth factor beta (TGF-β), which is a direct inducer of EMT." (PMID 37686525, 2023). "Leptin has been widely recognized as an important player in cancer biology in other malignancies, while its action in lung cancer is still controversial and under investigation." (PMID 37509120, 2023). "In contrast, Ann and colleagues found that leptin serum levels were lower in lung cancer patients compared to normal subjects." (PMID 37509120, 2023). "In this context, another of our previous pre-clinical studies on the effect of antioxidants on lung cancer, performed also with the A549 cell line, showed the role played by the flavonoid apigenin and the adipocytokine leptin in cell survival." (PMID 35740047, 2022). "Leptin seemed to mediate and amplify a complex interplay between tumor and immunoinflammatory cells, resulting in the development and progression of lung cancer." (PMID 36091512, 2022). "Consistently, the cell cycle-and apoptosis-related protein expressions of mTOR, STAT3, Bcl-2, and cyclin D1 significantly increased in A549 lung cancer cells after treatment with 100 ng/ml leptin." (PMID 33708630, 2021). "For the first time, we found that the PI3K/Akt/mTOR/STAT3 pathway was also involved in the effect of leptin on lung cancer cell growth." (PMID 33708630, 2021). "In vitro, leptin significantly increased the viability of lung cancer cell lines A549 and H460 in a dose-dependent manner by activation of STAT3, Bcl-2, and cyclin D1." (PMID 33708630, 2021). "The effect and potential mechanism of leptin on lung cancer cell growth was further demonstrated in vitro." (PMID 33708630, 2021). "Leptin was able to induce EMT in the lung cancer cell line A549, thereby promoting cell migration, invasion, and tumorigenesis." (PMID 33799880, 2021). "We showed that leptin significantly increased the viability of lung cancer cells A549/H460 in a dose-dependent manner." (PMID 33708630, 2021). "Leptin—Elevated expression of the hormone leptin is associated with reduced overall survival in NSCLC and promotes metastasis by inducing EMT in lung cancer cells." (PMID 34944848, 2021). "A549 and H460 lung cancer cells were treated with different concentrations of leptin for 48 h (0, 50, 100, and 200 ng/ml), and cell viability was determined using the CCK-8 assay." (PMID 33708630, 2021). "Compared to the control group (0 ng/ml), the cell viability of leptin-treated lung cancer cells increased significantly in a dose-dependent manner." (PMID 33708630, 2021).
lung cancer (continued). "Several published observations are in agreement with a decreased leptin level in lung cancer cachectic patients." (PMID 32660156, 2020). "Leptin can be detected in the microenvironment of several tumors, including breast and lung cancers, where it contributes to an aggressive tumor phenotype by inducing cell growth, migration, and invasion." (PMID 32289750, 2020). "Other studies have highlighted the prognostic role of serum leptin and adiponectin in patients with lung cancer." (PMID 33167545, 2020). "The results indicated that the positive expression of leptin protein is obviously higher in lung cancer tissue than in normal tissue, especially significantly higher in the lymph node metastases group." (PMID 28160559, 2017). "Many studies have found that leptin is involved in tumorigenesis and the progression of lung cancer." (PMID 28160559, 2017). "Further, a few studies have indicated that the expression of leptin protein was significantly higher in lung cancer tissues than in normal lung tissues." (PMID 28160559, 2017). "In the current meta-analysis, there were 14 primary studies comparing the blood leptin concentrations in lung cancer patients and healthy controls." (PMID 28160559, 2017). "In total, seven studies reported the role of leptin expression in lung cancer tissue, and all of these articles were conducted in China." (PMID 28160559, 2017). "Taken together, the results indicated a molecular link between leptin knockdown and viability as well as apoptosis in NSCLC cells, providing supporting evidence that leptin represents a target for lung cancer therapy." (PMID 27185268, 2016). "Leptin, mainly synthesized by adipocytes, is a pleiotropic molecule that is involved in tumorigenesis and the progression of lung cancer." (PMID 24932291, 2014). "As for lung cancer, the role of leptin as a growth factor, derived by data examining the effects of leptin in cell lines, requires validation by experimental studies examining its pathophysiological impact on cancer development." (PMID 21040518, 2010). "Leptin is a hormone secreted by adipocytes that has been shown to promote lung cancer progression and therapeutic resistance and thus may be considered a therapeutic target following lung-targeted RT." (PMID 40657241, 2025). "It is crucial to note that the specific mechanisms of leptin in lung cancer bone metastasis require further investigation due to the complexity of tumor metastasis and individual variability, which may lead to diverse leptin response patterns." (PMID 38571500, 2024). "Adipokines such as leptin and adiponectin have been shown to enhance lung cancer metastasis." (PMID 39512767, 2024). "Leptin can also upregulate the function of MDSCs, which suppress T cell activation and proliferation through the release of immunosuppressive factors and direct interaction with T cells, allowing lung cancer cells to evade immune surveillance." (PMID 38571500, 2024). "A clinical study involving 116 lung cancer patients with bone metastasis found significantly higher levels of leptin and its receptor in patients with bone metastases compared to those without, suggesting that the formation of lung adenocarcinoma bone metastatic lesions is closely related to leptin." (PMID 38571500, 2024). "Leptin’s indirect effects in lung cancer bone metastasis mainly involve regulation of OCs and OBs." (PMID 38571500, 2024). "Despite the debated role of leptin in lung cancer, in vitro and in vivo evidence has shown that this adipokine could promote the growth, migration, and invasion of lung cells." (PMID 37509120, 2023). "In fact, leptin might affect the epithelial-to-mesenchymal transition of A549, a widely used model for the lung cancer cell line." (PMID 37509120, 2023). "Prolonged sedentary behaviors are shown to increase the level of multiple inflammatory factors including tumor-necrosis factor-alpha, interleukin-6, and leptin that may contribute to the development of lung cancer." (PMID 34777480, 2021).
lung cancer (continued). "The observed overexpression of leptin and its receptors in our study may be a potential therapeutic target for endometrioid endometrial cancer, as it was previously proposed in lung cancer, however more research is needed." (PMID 34202922, 2021). "As a hormone secreted by fat cells and playing a key role in promoting angiogenesis, leptin is an important factor in the tumorigenesis, metastasis, resistance to apoptosis, and drug resistance of lung cancer and many other cancers by regulating various signal transduction pathways." (PMID 32903414, 2020). "It was also demonstrated that leptin promoted the development of lung cancer via JAK/STAT3 pathway." (PMID 31506433, 2019). "Therefore, we undertook a meta-analysis to determine the value of serum and tissue leptin in lung cancer." (PMID 28160559, 2017). "Additionally, a growing body of studies has found that leptin is also involved in tumorigenesis and the progression of lung cancer." (PMID 28160559, 2017). "Many studies have concluded that leptin may play a important role in the pathogenesis of lung cancer, but these results are inconsistent." (PMID 28160559, 2017). "Therefore, we performed a meta-analysis to investigate the role of leptin in the patients with lung cancer." (PMID 28160559, 2017). "The present meta-analysis suggests that the serum and tissue leptin may be involved in the pathogenesis of lung cancer and tumor metastasis, especially among Chinese." (PMID 28160559, 2017). "In summary, the current meta-analysis suggests that the serum and tissue leptin may play an important role in the pathogenesis of lung cancer and tumor metastasis, especially among Chinese." (PMID 28160559, 2017). "However, the subgroup analysis of ethnicity in the high-study quality group (NOS score≥7) indicated that the Chinese patients with lung cancer had higher serum leptin levels than the healthy population." (PMID 28160559, 2017). "Therefore, we also carried out a meta-analysis to investigate the role of tissue leptin protein expression in lung cancer." (PMID 28160559, 2017). "In summary, our results strongly suggested that for the first time, the role of leptin deletion could be a potential antitumor approach toward the treatment of lung cancer." (PMID 27185268, 2016). "In lung cancer, previous studies have reported that elevated serum leptin concentration in NSCLC patients may be involved in the development of non small-cell lung carcinogenesis independent of central obesity." (PMID 27185268, 2016). "Our findings suggested that leptin knockdown could become a new approach for the prevention of lung cancer progression, which is likely to be mediated at least partially by inactivation of the Notch and JAK/STAT3 signaling pathways." (PMID 27185268, 2016). "Additionally, factors such as lung cancer type (e.g., adenocarcinoma, squamous cell carcinoma), molecular subtypes, and the microenvironment may also influence the effects of leptin." (PMID 38571500, 2024). "This review primarily explores the role of BMAs and their secreted adipokines (leptin, adiponectin, Nesfatin-1, Resistin, chemerin, visfatin) in lung cancer bone metastasis, aiming to provide new insights into the mechanisms and clinical treatment of lung cancer bone metastasis." (PMID 38571500, 2024). "Thus, leptin was able to promote the migration and invasion of lung cancer cells." (PMID 37509120, 2023). "Furthermore, leptin could stimulate the proliferation of lung cancer cells in a PI3K/Akt/mTOR-dependent manner in vitro." (PMID 33708630, 2021).
lung cancer (continued). "Interestingly, in humans the expression and clinical importance of leptin in lung cancer is a relevant since, in both serum and tissue samples, the leptin levels of the group of patients with lung cancer were significantly higher in comparison with those of the control group." (PMID 33334030, 2020). "Among them, some studies have found that elevated serum leptin levels represent an independent risk factor for non-small-cell lung cancer (NSCLC), whereas other studies have reported significant correlation between decreased serum leptin levels and prognosis in lung cancer." (PMID 28160559, 2017). "However, the observed relationships of these studies were inconsistent, and a single study may lack sufficient power to detect the possible small effect of the leptin levels on lung cancer, especially when the sample size is relatively small." (PMID 28160559, 2017). "According to the experimental evidence that leptin, JAK/STAT3, and Notch are intimate partners in crime with regard to tumorigenesis, we hypothesize that targeting inactivation of these pathways by leptin knockdown may be a novel treatment approach for lung cancer." (PMID 27185268, 2016). "BMAs can also secrete certain adipokines, such as leptin, by activating signaling pathways such as PI3K, HIF, and MAPK, enhancing the proliferation, migration, and invasion capabilities of lung cancer cells." (PMID 38571500, 2024). "Leptin can upregulate GRP78 expression through the PI3K/TOR/STAT3 signaling pathway in neuronal and lung cancer cells." (PMID 33708630, 2021). "The elevated leptin level in the patient’s serum is correlated with the severity of lung fibrosis and leptin and significantly promotes EMT in A549 lung cancer cells, as evidenced by increased collagen I and α-SMA expression." (PMID 33334030, 2020). "Leptin also induces EMT and expression of the transcription factors ZEB and Twist via activation of the ERK signaling pathway in A549 lung cancer cells." (PMID 33334030, 2020). "Leptin promotes invasion and metastasis by inducing EMT in A549 lung cancer cells by the upregulation of mesenchymal markers such as vimentin, N-cadherin, and Twist, and the downregulation of epithelial markers E-cadherin and β-catenin." (PMID 33334030, 2020). "The over-expressing variant is associated with earlier onset of lung cancer, but not with advanced metastatic disease, suggesting that continuous exposure to higher leptin concentrations due to the polymorphism in the leptin gene may accelerate cancer initiation." (PMID 21040518, 2010). "Leptin dose-dependently promotes naïve CD4+ T cell proliferation and polarizes CD4+ T cells towards a Th1 phenotype, which in turn facilitates lung cancer secretion of inflammatory cytokines such as TNF-α and IL-6, promoting lung cancer bone metastasis." (PMID 38571500, 2024). "Moreover, leptin, through a mechanism dependent on the activation of the ERK signaling pathway, increases EMT-induced tumor phenotypes in lung cancer cells too." (PMID 37686525, 2023). "Moreover, CAAs can produce leptin, which has been demonstrated to promote EMT changes in A549 lung cancer cells, contributing to tumor cell mobility and consequently their invasiveness in the bone." (PMID 33262947, 2020). "The overall results indicated that the serum leptin levels did not increase in the patients with lung cancer, as compared with the controls." (PMID 28160559, 2017). "After further, full-view screening, nine articles were excluded because they were not relevant to lung cancer in relation to serum leptin concentrations and/or the leptin protein expression levels of tissue." (PMID 28160559, 2017). "Thus, even though the mechanism remains completely unclear, we speculate that leptin may play an important role in the pathogenesis of lung cancer and tumor metastasis, and the increased serum leptin level may possibly predict the diagnosis and progression of lung cancer." (PMID 28160559, 2017).
lung cancer (continued). "Moreover, they did not report any significant differences in leptin values related to clinicopathological parameters, sustaining that leptin has no prognostic value in lung cancer patients." (PMID 37509120, 2023). "However, previous evidence has suggested that there is no clear relationship between serum leptin concentrations and lung cancer progression." (PMID 31119158, 2019). "On the other hand, a recent meta-analysis suggested that there may be no clear relationship between the serum leptin concentration and lung cancer progression." (PMID 31119158, 2019). "We further analyzed the results by the lung cancer types, and the results showed that the serum leptin levels were not statistically different between the NSCLC group and the SCLC group (NSCLC: SMD=-0.53, 95%CI=-1.92–0.86, P=0.454; SCLC: SMD=-0.23, 95%CI=-0.64–0.18, P=0.270)." (PMID 28160559, 2017). "Leptin system plays an important role in lung inflammation and tumorigenesis, but the precise function in the tumormicrovironment and the prognosis value of the leptin system in lung cancer have not been fully elucidated." (PMID 24758911, 2014). "Therefore, translational research targeting leptin and/or its receptor as therapeutic molecules and design of NSCLC animal experiments that mimic treatment regimens might be promising as therapeutic strategies for NSCLC cancer treatment, driving progress in the field of lung cancer research." (PMID 38418632, 2024).